IL4 (interleukin 4)
Diseases named in the same sentence as IL4 in open-access papers (continued):
Sharing a sentence is not in itself a finding about the gene and the disease.
infection (continued). "In order to explain the reduced SF162 (R5) infection in Th2 cell cultures induced by SEA exposed DCs we characterized the cytokine/chemokine (IFN-γ, IL-4, IL-2, TNF-α, MIP-1β) expression profiles of the different Th cell populations." (PMID 31487324, 2019). "Our results show that infection with this protozoan influences the peripheral and placental immune response and that it is mediated by a mixed of Th1 (IFN-γ and TNF-α), Th2 (IL4) and Treg (IL10) cytokines." (PMID 31533826, 2019). "Like natural infection, a gradual surge in the levels of IL-4, IL-10, and TGF-β were observed, while the levels of IFN-γ and TNF-α increased gradually at early infection but were reduced to basal level at chronic infection." (PMID 31031744, 2019). "Interleukins (IL), namely IL-2, IL-4, IL-8, and IL-10, and interferons (IFN), IFN-γ and IFN-α, were identified as the main mediators in mice and cotton rats following infection with hMPV." (PMID 31271048, 2019). "In contrast, mb1creIL-4Rα−/lox mice developed significantly increased levels of IL-4, IL-10, IL-6, IL-17, and IFN- γ compared to IL-4Rα−/lox littermate control mice at 24 weeks post infection." (PMID 30619289, 2018). "Not only the percentages of MHC II-, CD69-, and NKG2A/C/E-expressing cells but also the percentages of IL-4-, IL-5-, and IL-17-producing cells in TLR3+ NK cells increased significantly after infection (P < 0.05)." (PMID 30246036, 2018). "Lung infiltrating leukocytes from DT-treated and untreated DEREG mice were obtained at weeks 6 and 10 after infection and intracellular presence of IFN-γ+, IL-4+ and IL-17+ in CD4+ and CD8+ T cells was assessed by flow cytometry." (PMID 30410119, 2018). "To gain insight into the spatial distribution of these IL-4-producing NKT cells, we infected wild-type, CD1d−/−, and IL-4 GFP reporter mice with influenza virus and harvested mediastinal lymph nodes after infection." (PMID 29249358, 2018). "In both groups of animals, infection with Colombian strain induced a significant increase in TNF-α (NI WT vs. Inf WT, p = 0.02, t = 2.61 and NI IL-4−/− vs. Inf IL-4−/−, p = 0.002, t = 4.74)." (PMID 30622430, 2018). "Pre-colonization by NPI followed by CP1-infection showed increased VEGF and IL4 expression when compared to CP1-alone (analysis 3) and decreased levels of CCL2/3 and 4, and IL17." (PMID 30479364, 2018). "Infection had a similar effect on diabetic animals (DATCC), inducing an 8-fold increase in the IL-4 level in comparison with that of uninfected diabetic controls (Ds)." (PMID 30705678, 2018). "The levels of IL-4 and IFN-γ were also elevated in gnotobiotic pigs after infection with virulent or attenuated human rotavirus." (PMID 29466421, 2018). "Specifically, both the CH and CH60 strains inhibited IL-4 and TNF-α expression during the early stage of infection, and both cytokines were up-regulated after 60 hpi." (PMID 29700351, 2018). "To get insight into the extent of cellular heterogeneity within the immune cells contributing to the early IL-4 wave, we characterized the IL-4 GFP+ population by flow cytometry 3 days post-infection with influenza virus." (PMID 29249358, 2018). "In the liver on day 7 post-infection, the expression of iNOS, IL-1β, IL-6, IL-12 p40, TNF-α, IL-10, TGF-β, CCR2, CCL2, IFN-γ and IL-4 was significantly up-regulated, and the expression of Arg-1 was down-regulated in both of MRP14-KO mice and WT mice." (PMID 29902248, 2018). "To investigate lymphocyte activity after infection, we quantitatively determined the presence of IL-2, IFN-γ, TNF-α, IL-4, IL-5, IL-17A, IL-12p70, and IL-22 in mouse sera at day 3, 5, 7, and 9 post-infection; the sera of healthy mice were used as controls." (PMID 30564216, 2018). "The cytokines IL-12 and IL-4 induce CAT2B expression and the uptake of L-arginine, a substrate of ARG1 and NOS2, altering outcome of infection, while the negative regulation of CAT2B expression also reduces the infectivity of L. amazonensis." (PMID 30555476, 2018).
infection (continued). "Subsequently, to check whether the recovery of the initial IL-4 wave could rescue the germinal center defect observed in NKT cell-deficient mice, we administered PBS or IL-4 complexed with an anti-IL4 antibody (IL-4c) to groups of CD1d−/− mice during the initial 2 days of infection." (PMID 29249358, 2018). "The expression of IFN-γ was significantly increased (p < 0.001) during infection in both the PL16 and TL16 groups, while IL-4 remained stable." (PMID 28577529, 2017). "In vivo, we found that that the expression levels of IL-2, IL-4, IL-6 and TNF-a in the lungs of H9N2 infected mice peaked on 2 days post-infection and then declined on days 4 and 6 post-infection." (PMID 28114957, 2017). "Following infection, expression levels of the immunomodulatory cytokines C-C motif chemokine 22 (CCL22), CCL1, IL-23α, IL-3, IL-4, matrix metalloproteinase 9 (MMP9), IL-21, C-X-C motif chemokine 2 (CXCL2), and CCL2 were increased." (PMID 28507072, 2017). "The simulator agrees with key experimental results published in the literature such as the antagonism between IL-4 and IFN-γ and brings new lights to the influence of Ado signaling in these infections." (PMID 28775959, 2017). "Serum levels of IFN-γ, IL-4, IL-10 and IL-17 were determined by IVCCA at 0, 3, 5, 7, 10 and 12 wks post infection." (PMID 28614408, 2017). "Combination of detecting level of TNF-α/IL-4 balance, CSS antigen and IgG concentration is good tool for appropriate diagnosis of such infection." (PMID 28717322, 2017). "A proportional relationship between antibodies and infection was found, but for appropriate diagnosis, TNF-α (Th1) and IL-4 (Th2) were measured." (PMID 28717322, 2017). "Circulatory IFN-γ, IL-4, IL-5, IL-6 and TNF-α were increased in WT mice after infection with PcAS (respectively, p = 0.004, 0.004, 0.0081, 0.004 and 0.004)." (PMID 29062028, 2017). "The levels of IL-4 and MCP-1, involved in the recruitment of eosinophils and macrophages respectively, also increased significantly later during the infection at d4 and/or to d8 p.i. and their production was correlated." (PMID 28486498, 2017). "Two weeks post infection, the frequency of CD4+IFNγ+ and CD4+IL-4+ dLN T cells represented in average 0.6 and 0.13% of total CD4+ T cells, respectively." (PMID 29067025, 2017). "As a result, the ratio of IFN-γ/IL-4 in the serum of mice treated with mixed LAB was reduced in the protection and treatment groups between infection and recovery." (PMID 28819629, 2017). "To ascertain this FACS data, we determined the relative expression of Th2 and Treg related cytokines (IL-4, IL-5, IL-10 and TGF-β) in the liver of non-infection and C. sinensis infection mice by the quantitative RT-PCR." (PMID 28151995, 2017). "Analysis of cytokines production by spleen and MLN cells in mice model have shown the production of IL-4, IL-10, IL-13, IL-17, IL-22, TNF-α, and IFN-γ after infection with both WB and GS strains." (PMID 28979269, 2017). "Production of Th2 cytokines (IL-4, IL-5, IL-10 and IL-13) by MLN cells similarly peaked at day 6–7 post infection and gradually declined thereafter." (PMID 28651009, 2017). "After challenge with B. microti, the levels of cytokines including IL-17, IL-4, IL-6, IL-10, IL-12p70, G-CSF, IFN-γ, TNF-α, IL-2, GM-CSF, MCP-1, MIP-1α, MIP-1β, and MIP-2 in the serum of the BMSA vaccinated group changed as infection progressed." (PMID 29312230, 2017). "The expression levels of IL-2, IL-4, IL-6 and TNF-α in calcitriol-treated infected mice were significantly lower than the untreated infected mice on 2 days post-infection (p <0.01)." (PMID 28114957, 2017). "IL-18 was lower on day 2 than at baseline in asthmatics and significantly lower in asthmatic compared to normal subjects on day 4 and IL-4 and CCL13/MCP-4 were also decreased after infection in asthmatics on days 5 and 7 and day 2 respectively." (PMID 28373098, 2017).
infection (continued). "We also found that in contrast to serum IL-4, serum IFN-γ increased in the PL16 and TL16 groups during infection and returned to normal during convalescence, consistent with previous observations." (PMID 28577529, 2017). "In the sera of M. fortis, the levels of IL-1b, IL-3, IL-4, IL-10, IL-17, MCP-1 and VGF were found to increase from the second to the third week post-infection." (PMID 28900150, 2017). "Thirty days post infection, chitosan treatment resulted in MPO, MCP-1, TNF-α, IL-12p70 and IL-4 levels falling to control values, but IL-6, IL-10 and TGF-β were elevated." (PMID 29156562, 2017). "Infection studies with L. major LV39 and IL81 in the footpad revealed that IL-4-mediated instruction of DCs occurs in vivo with biological quantities of IL-4 acting on DCs to promote protective immunity." (PMID 29176972, 2017). "In that setting, IL-4 DCs were able to transfer significant amounts of HTLV-1, while reduced luciferase signals were detected using LPS-treated IL-4 DCs or IFN-α DCs, confirming that productive infection is required to allow virus transfer to T-cells." (PMID 28426803, 2017). "Infection of BALB/c mice by Leishmania amazonensis led to higher accumulation of Langerhans cells, and CD4+ and CD8+ T cells were found that produced IL-4 and IL-10." (PMID 27536300, 2016). "There was a significant increase at day 7 relative to day 5 post-infection in abundance of interleukins (IL) including IL1B, IL2, IL4, IL5, IL6, IL10 and IL13." (PMID 27311020, 2016). "Lung CD8+ T-cell subsets were then examined at 2 and 4 days post-secondary infection: GM-CSF+ CD8+ T cells (respectively), IL-4+ CD8+ T cells (respectively), IFN-γ+ CD8+ T cells (respectively), and IL-17+ CD8+ T cells (respectively)." (PMID 27242785, 2016). "Serum IL-4 levels in vaccinated sheep were higher than those in the PBS group after the immunization (P < 0.01) and peaked after the infection(P < 0.01)." (PMID 27094043, 2016). "Lung CD4+ T-cell subsets were then examined at 2 and 4 days post-secondary infection: GM-CSF+ CD4+ T cells (respectively), IL-4+ CD4+ T cells (respectively), IFN-γ+ CD4+ T cells (respectively), and IL-17+ CD4+ T cells (respectively)." (PMID 27242785, 2016). "Thirty days after treatment all interleukins levels reveal changes due to infection; while IFN-γ, IL-4, and IL-12 decreased (PC < NC), IL-10 increased (PC > NC)." (PMID 27303789, 2016). "We also detected increased levels for IL-1α, IL-4, IL-10 and M-CSF, implying that these cytokines, along with IL-12 and INF-γ, play important roles in controlling the infection and confining the chronic infection in inactive state." (PMID 27895319, 2016). "In contrast, the increased levels of two immunosuppressive cytokines (IL-4 and IL-10) were observed during AG83+Sias infection which was declined significantly (p≤ 0.05) during AG83-Sias and UR6 infection." (PMID 27494323, 2016). "On the other hand, thefrequency of IL-4 and IFN-γ double producers increased in MAT andOAT 7 and 21 days after infection and also in SAT 21 days after infection." (PMID 27001522, 2016). "Under these conditions, primary infections resulted in the development of a local Th1 phenotype as shown by upregulation of IFN-γ and low levels of IL-4 and IL-13." (PMID 27658962, 2016). "However, some general points can be made: Th2-associated cytokine levels were higher overall, as might be expected given the nature of the infection; IL-3, IL-4, IL-5, IL-10 and IL-13, were all elevated in popLN cells from infected limbs, particularly so when re-stimulated with Brugia antigen." (PMID 27992545, 2016). "The study demonstrated that TGF-β and IL-4 are up-regulated as a consequence of F. hepatica infection, TGF-β reaches its maximum levels of serum at week 2 post infection in each mouse." (PMID 27681524, 2016). "Towards the terminal stage of infection, on day 6, transcript levels of some cytokines in HA-MARV-infected animals began to significantly increase, notably IL-6 and IL-4." (PMID 27976688, 2016).
infection (continued). "In this research, though the magnitude and duration of each cytokine differed between the two Listeria, the trends along with infection are same, which are increase of TNF-α, IL-6, IL-12, and IFN-γ and decrease of IL-4." (PMID 27375558, 2016). "Due to infection of macrophages with AG83+Sias, reduction of the genetic expression of Th1 cytokine genes (IFNγ and IL-2) and upregulation of Th2 cytokine genes (IL-4, IL-10 and TGFβ) were observed." (PMID 27494323, 2016). "In vivo, infection of Kdm5bfl/fl-CD11c-Cre+ mice with RSV resulted in higher production of IFN-γ and reduced IL-4 and IL-5 compared to littermate controls, with significantly decreased inflammation, IL-13, and mucus production in the lungs." (PMID 26083387, 2015). "To test the contribution of these cells to the IL-10 produced in the early phase of infection, we measured the proportions of CD4+ Foxp3− IL-10+ T cells coexpressing IFN-γ and IL-4." (PMID 26195548, 2015). "Measurement of the bacterial load at different time-points post-infection showed significantly lower colony-forming units (CFU) in the M1 (IFN-γ+LPS) group, while that in the M2 (IL-4) group was notably higher compared with that in the M0 (un-induced) group." (PMID 26091535, 2015). "In the experimental mouse model, during the initiation of the infection, (early stage AE) both Th1 (IFN-γ) and Th2 (IL-4) related cytokines are present; but an initial dominance by Th1 cytokines and chemokines has been evidenced." (PMID 26053794, 2015). "Historically, low levels of T cell cytokines (IL-2, IL-3, IL-4, IL-5, IL-9, IL-13) have been observed in fatal human cases of infection with EBOV and in infection of NHPs with MARV." (PMID 26512687, 2015). "This strategy allowed us to track the response of IL-4-induced and Eomes- conventional CD8+ T cells after CL–13 infection and to judge their individual contributions to the protection against viral persistence." (PMID 26452143, 2015). "In contrast, 24 weeks of infection induced new changes in other inflammatory molecules with reduced KC, MCSF, enhancing GM-CSF, IFNγ, IL-1β, IL-13, IL-4, IL-13, lymphotactin, RANTES, and also an increase in select inflammatory molecules." (PMID 26619277, 2015). "Eighteen cytokines were elevated >2-fold relative to controls at 12 weeks of infection, including CD 30L, Fas ligand, Fractalkine, GCSF, IFN-γ, IL1-β, IL4, IL10, IL12p40/p70, IL12p70, IL17, I-TAC, Lymphotactin, MCP-1, MCSF, MIG, MIP-1α, and TIMP-2." (PMID 26079509, 2015). "Increased expression of Ccl24, CCR3, IL4 and Pdgfc in C57BL/6J mice compared to that in Trim55-/- mice at day four post infection correlates with increased inflammatory cell recruitment and binding to extracellular matrix proteins." (PMID 26452100, 2015). "At week 6 post-infection, mice receiving CD4+Foxp3- T cells + Treg showed the greatest numbers of cells producing IFN-γ, IL-17 and IL-4." (PMID 26512987, 2015). "However following infection of IL-4Rα-/- mice, which are compromised in their capacity to generate a Th2 response, they found similar changes in the gut microbiota composition, indicating that the hookworm was able to alter the microbiota independently of the IL-4-regulated adaptive Th2 response." (PMID 25942314, 2015). "Whereas, hydatid crude antigen induced expression of IL-4, IL-5, IL-6 and IFN-γ in PBMCs isolated from patients and showed correlation with the infection status." (PMID 26578348, 2015). "In the present study, we demonstrated that IL-4-induced innate CD8+ T cells are able to rapidly proliferate, secrete cytokines, and decrease viral load after LCMV CL–13 infection." (PMID 26452143, 2015). "In vitro infection further increased the generation of NO2−, and IL-4 alleviated both the NO2− generation-induced by the bacteria alone (p < 0.01) and by the combined actions of infection, IFNγ and TNFα (p < 0.01)." (PMID 26481427, 2015).
infection (continued). "We developed and employed two different mathematical models to explain the MAP experimental infection data (IL-10, IFN-γ (Th1), IL-4 (Th2), and CFU (bacteria)) from calves that were followed over a period of 360 days in the study." (PMID 26619346, 2015). "We tested the developed models with MAP experimental infection data from the study of Stabel and Robbe-Austerman where calves were challenged with MAP and several immune variables were measured (IL-10, IL-4, IFN-γ and MAP CFUs." (PMID 26619346, 2015). "An expansion of CD38+ CD69+ T cells in the acute phase compared to the resolving phase of infection with an increased in mRNA expression of IFN-gamma, TNF-α and IL-4 has reflected an increment in CD3+ CD38+ CD69+ T cells." (PMID 24963498, 2014). "We found no activation or even reduction in base-line expression for multiple molecules (IL-7, IL-4, IL-13, GATA3, ROR-γt, and CXCL12) at 2, 6 and 10 days post-infection." (PMID 25254971, 2014). "Although a high IFN-γ:IL-4 ratio (1.34) was observed demonstrating Th1 bias, a low IFN-γ:IL-10 ratio (0.6) was found to correlate with the exacerbation of infection in spleen observed following L. donovani challenge." (PMID 24428931, 2014). "In this context, the ratios between IL-12/IL-4 and IL-12/IL-10, and between IFN-γ/IL-4 and IFN-γ/IL-10, indicated that vaccinated mice developed a Th1 response, which was maintained after infection." (PMID 25333662, 2014). "IFN-γ and IL-4 were also produced in antigen-specific PBMC stimulation analyses, at the end of the first and during the second week following infection with N. caninum and prior to mounting a specific IgG response." (PMID 24479988, 2014). "Similarly, basophils are known to act as effectors to promote parasite killing during challenge infections of immunized animals, perhaps through antibody dependent mechanisms, while neutrophils have been demonstrated to attack helminth larvae in response to IL-4 and IL-5." (PMID 24498448, 2014). "Th1 and Th2 cells are specialized subsets of CD4+ T helper cells that respond to different modes of infection and which express the signature cytokines IFN-γ and IL-4, respectively." (PMID 24578067, 2014). "IL-2+ and IL-4+ secreting cells showed significant increase 12 days post infection, while IFN-γ+, IgG+ and IgA+ secreting cells increased 6 days post infection." (PMID 24725777, 2014). "On day 8 post-infection, cells were collected and stained for extracellular expression of CD4 and CD25, and intracellular expression of IFN-γ, IL-4, IL-17A, and Foxp3." (PMID 24918929, 2014). "Our results demonstrated that higher levels of IL-12, IL-1β, IL-4 (Th2) and IFN-γ (Th1) were produced following infection of BMDCs with the recombinant virus than with the control virus." (PMID 25420583, 2014). "The severe infection group had significantly lower levels of IFN-γ, IL-4, IL-10, IL-15, and IFN-α2 during the CP than during the AP." (PMID 24646014, 2014). "Compared with uninfected mice, infected wild-type mice showed higher levels of IL-4, IL-10 and IL-13, with similar levels of α-smooth muscle actin, galectin-3, TGF-β1, IL-17, IFN-γ, and lower IL-12 levels at 90 days post-infection." (PMID 25032961, 2014). "In both models of infection, protection was correlated to parasite antigen-specific production of IFN-γ and down-regulation of parasite-mediated IL-4 and IL-10 responses." (PMID 24382098, 2014). "Levels of IL-4, IL-5, IL-8, IL-12/23p40, IL-17, G-CSF, GM-CSF, sCD40, and RANTES were either unchanged in post-infection samples or below levels of detection." (PMID 25412185, 2014). "This study provided some basic data on the optimal time to observe different immune parameters, for example, IL-2+, IL-4+ CSCs stimulated about 12 days post infection, TNF-α, IFN-γ, IL-10 cytokines only transiently increased in the early infection." (PMID 24725777, 2014).